NOTCH1 (notch receptor 1)
Diseases named in the same sentence as NOTCH1 in open-access papers (continued):
Sharing a sentence is not in itself a finding about the gene and the disease.
tumor (continued). "When similar experiments were repeated with a mixture of cells infected with a retrovirus expressing activated-Notch1 together with GFP, little or no GFP-positive tumor areas were detected, consistent with the long term growth suppressing effects of activated Notch1 in culture." (PMID 27384993, 2016). "In addition, ∼70% of Notch1-positive GBM cells showed high expression of TUG1 in the perivascular regions, whereas in areas distant from tumour vessels, the majority of GBM cells expressed neither Notch1 nor TUG1." (PMID 27922002, 2016). "Notch4, but not Notch1-3 was shown to contribute to the induction of proliferation, tumorigenesis and invasiveness in TNBC cells and its inhibition was shown to suppress tumorigenicity and tumor volume." (PMID 26713603, 2016). "Having previously reported that Notch3 activation appeared to be associated with more aggressive disease, we have now examined components of this pathway (Notch1, Notch3, Notch4, HES-1, HEY-1) in more detail in resectable (n = 42) and non-resectable (n = 50) tumours compared to uninvolved pancreas." (PMID 23226563, 2012). "Since Notch1 was indicated in promotion of tumor invasion, metastasis and EMT, a feature related to cancer stem cells, and Notch1 expressed in one cell line, but not in another, we were attempted to assess whether these two cell lines had different 5-FU response." (PMID 23409141, 2013). "Therefore, it is hypothesized that the tumor spectrum of Sdl mice is, at least in part, due to the propensity to develop type 2 non-RAG driven deletions at the Notch1 locus." (PMID 23133403, 2012). "Given the fact that these tumor cells also coexpress ADAM10 and activated Notch1, ADAM10/Notch1 signaling might also participate in this process, as recent studies have demonstrated that ADAM10 and Notch1 could promote the migration of a variety of tumor cells, both cooperatively and individually." (PMID 24548763, 2014).
cancer (1,127 papers, 2005 to 2026). A tumor composed of atypical neoplastic, often pleomorphic cells that invade other tissues. "Additional cooperating mutations in known cancer genes (including Nf1, Ep300, Notch1, Sbds, and Ets1) were identified in 5 of the 9 GAB2 mAMLs." (PMID 40773291, 2025). "Studies have identified that cancer stages with immune suppression are strongly associated with elevated NOTCH1 expression levels." (PMID 40672020, 2025). "Recently, β-1,4-GalT-V has been implicated in stem cell differentiation and the glycosylation of Notch-1, a cancer- and angiogenesis-associated transmembrane protein." (PMID 40869407, 2025). "We confirmed these cancer‐favorable properties are closely associated with the Notch1 signaling pathway, which is most prominently activated in malignant AP2M1+ HSPCs of human samples." (PMID 41082341, 2025). "NOTCH1 mutations, recognized as prognostic biomarkers in various cancers, including HNSCC, are known to influence cell differentiation, proliferation and apoptosis." (PMID 40588522, 2025). "For example, recent studies have found that NOTCH1 mutations can confer a fitness advantage that promotes clonal expansion while minimally affecting cancer risk." (PMID 40929164, 2025). "Other known mechanism for up-regulation of GATA3 expression include transcriptional activation by cancer-associated pathways as the NOTCH1 and NFkB pathway as well as GATA3 promoter hypomethylations." (PMID 39979991, 2025). "DLL4 monoclonal antibodies, which were associated with PH in cancer patients, have been recently shown to cause pulmonary vascular remodeling and PH in mice through the inhibition of endothelial NOTCH1 signaling." (PMID 38903104, 2024). "We found altered expression in the cancer stemness-associated gene NOTCH-1 and its corresponding protein." (PMID 38397874, 2024). "Notch1 signaling is a major pathway involved in cancer progression that is influenced by ASPH, but the underlying mechanisms of the influence of ASPH on the noncanonical pathway involved in this interaction have not been determined." (PMID 38817852, 2024). "Altogether, this study elucidated the mechanism of action of three distinct cannabinoids in modulating the Notch1 pathway, and constitutes an important step in the establishment of a new therapy for treating NOTCH1-mutated diseases and cancers such as T-ALL." (PMID 39258755, 2024). "By affecting the expression of different genes, lncRNA is involved in the regulation of a variety of cellular signaling pathways, including the nuclear factor-κB (NF-κB), Wnt/β-catenin, and NOTCH1 signaling pathways, which are closely associated with cancer." (PMID 38532427, 2024). "Notch1 is a crucial component of the Notch signaling pathway and has been linked to various types of cancer, including T-acute lymphoblastic leukemia." (PMID 39063983, 2024). "Both neuroendocrine cancer cells, and cells with more epithelial differentiation, which coexist in this cancer side by side, showed inactivating and activating NOTCH1 mutations, respectively." (PMID 37760535, 2023). "In total, 22% of primary EBV + DLBCLs (10/46) harbored mutations affecting NOTCH1 or NOTCH2. dNdScv confirmed both genes as significant cancer driver genes." (PMID 36604606, 2023). "Special AT-rich sequence-binding protein 1 (Satb1) derived cancer-associated dendritic cells (DCs) differentiation by activating NOTCH1 signaling to regulate major histocompatibility complex class II (MHC II) expression." (PMID 37386521, 2023). "SERCA was first identified by genomic screens as a potential target in cancer cells that harbor mutated NOTCH1." (PMID 37760535, 2023).
cancer (continued). "Oncogene NOTCH1 displayed also higher mutation rates in basal ER-negative/HER2-negative cancers, being the third most frequently mutated gene in this group." (PMID 37345027, 2023). "High NOTCH1 activity has been also linked with several other types of cancers including lymphomas and brain, breast, lung, ovarian, renal, and hepatocellular cancer." (PMID 37628760, 2023). "A previous report has also demonstrated the multiple mutations of various key players in the regulation of cancer initiation and progression, including Notch1, in PTCL patients." (PMID 36768603, 2023). "Tumor suppressor miRNA, miR34a, is believed to be frequently depleted in cancer tissues and it is associated with the genetic expression of multiple signaling pathways, including NOTCH-1, CD44, Bcl-2, Myc, Met, CDK-4/6, and various other biological molecules." (PMID 37149609, 2023). "This high prevalence of NOTCH1 mutations in normal tissue and absence in cancer represents a cryptic phenomenon." (PMID 37573406, 2023). "HDACis inhibit the activity of cancer stem cells by targeting several essential genes involved in cancer stem cell maintenance, such as those encoding β, γ-catenin, Stat3, and Notch1, thereby reducing tumor development." (PMID 36810560, 2023). "The frequency of NOTCH1 mutant clones in the esophagus outpaces their frequency in associated carcinomas, indicating selection against NOTCH1 disruption during cancer evolution." (PMID 35726685, 2022). "Notch1 is a Notch receptor and is dysregulated in a variety of cancer types; however, the underlying mechanism between Notch1 and PC needs to be studied further." (PMID 36351890, 2022). "The WES also allowed us to identify CNV-seq in 42 cancer-associated genes with cn > 3, including NOTCH1, MYC, NUMA1, PLAG1, and RAD21 amplified in 10% of tumors." (PMID 35884575, 2022). "The CNV analysis by sequencing (CNV-seq) revealed five cancer-associated genes as the most frequent with gains (NOTCH1, MYC, NUMA1, PLAG1, and RAD21), while 30% of the tumors showed SMARCA4 with loss." (PMID 35884575, 2022). "Among them, five cancer-associated genes were confirmed by both analyses as the most frequent genes with gains: NOTCH1, MYC, NUMA1, PLAG1, and RAD21." (PMID 35884575, 2022). "In human cancers, somatic mutations of NOTCH1 generally cluster in two main hotspots: the HD and PEST domains." (PMID 35740661, 2022). "The most common mutations that appear to drive clonal expansions in this tissue are in the NOTCH1 gene, and these mutations are very similar to those found in human cancers." (PMID 35726685, 2022). "We noticed that some cancer-related genes such as NOTCH1/2 were mutated in the esophageal PNM of both GC and ESCC, but the mutation frequency in GC was relatively lower than that in ESCC." (PMID 35515115, 2022). "Sequencing of the HNSCC genome revealed that NOTCH1 acts as a tumour suppressor gene and that it is the second most frequently mutated gene in this cancer, with an incidence of 15–19%." (PMID 35739348, 2022). "NOTCH1 variants are found in many cancer types (cBioPortal) suggesting its pathogenic role in cancer growth, invasion, and metastasis." (PMID 35186194, 2022). "Future studies in NOTCH1-mutant cancers will be facilitated by the validation of our algorithm to predict NOTCH1 mutation function and the ability to detect NOTCH1 mutations in blood." (PMID 36124629, 2022). "The first report implicating Notch mutations in cancer dates back to the observation in the early 1990s of translocations in the NOTCH1 locus identified in patients with acute lymphoblastic T-cell leukemia (T-ALL)." (PMID 35682918, 2022).
cancer (continued). "When activated in cancer cells, members of the Notch family, such as Notch1 and its ligands Dll4 and Jagged1, are linked to proliferation, survival, and progression." (PMID 35480877, 2022). "Mammals possess four different Notch receptors, NOTCH1-4, all of which have been identified as mutated—with very different frequencies—in diverse human cancers." (PMID 34944837, 2021). "Similar to human cancers, the Notch1 missense variants were found to cluster in the heterodimerization domain (HD) while frameshift or nonsense variants were clustered to the proline–glutamic acid–serine–threonine (PEST) domain." (PMID 34771656, 2021). "Together with other ion flux modulators, SERCA emerged as a novel potential therapeutic target in NOTCH1-associated cancers." (PMID 33407740, 2021). "In a systematic interactome study, we previously showed that EXT1, an ER-resident type II transmembrane glycosyltransferase, interacts with Notch1, a type I transmembrane receptor that is frequently mutated in cancers." (PMID 33962942, 2021). "Most patients have additional mutations in other cancer-related genes such as activating mutations in the NOTCH1 and ERBB3 receptors and regulators of signal transduction and cell cycle." (PMID 33733072, 2021). "Here we update on the current scientific advancements to impede NOTCH1 transfer to the cell surface by blocking SERCA activity as a strategy to target NOTCH1-mutated cancers." (PMID 33407740, 2021). "Using the Sleeping Beauty transposon system in Brca1-deficient mice, we identified 169 putative cancer drivers, among which Notch1 is a top candidate for accelerating TNBC by promoting the epithelial-mesenchymal transition (EMT) and regulating the cell cycle." (PMID 32591500, 2020). "A more precise algorithm that takes these and other confounding issues into account while predicting the likely functional impact of NOTCH1 mutations in cancer patients is currently under development by our group (manuscript in preparation)." (PMID 33322834, 2020). "Sequentially, NOTCH1 downregulation reduces uPA expression, causing an anti-cancer positive feedback loop." (PMID 33003595, 2020). "All four NOTCH receptors described in mammals (NOTCH1, 2, 3 and 4) have been implicated in cancer, with peculiar context-dependent associations." (PMID 32796631, 2020). "Given the high frequency of activating NOTCH1 mutations in cancers, especially in T-ALL, the inhibition of the γ-secretase complex has represented a rational target to hijack the ligand-independent release of N-ICD for many years." (PMID 33003595, 2020). "This approach sets the ground for the development of inhibitors with dual selectivity: cancer over normal cells and NOTCH1 mutated over wild-type targets." (PMID 33003595, 2020). "Although ligand-induced activation of Notch signaling that involves a conformational change of the NRR is considered a major activating pathway, the activating mutations in the NRR and/or the PEST domain of Notch1 are seen in over 50% of cancer cases." (PMID 32630477, 2020). "Especially NOTCH1, where 70% plasma samples exhibited at least one mutation, highlighting the unique values of plasma in detecting cancer mutations." (PMID 31369215, 2019). "This is consistent with the known important role of glycosylation in Notch signaling, suggesting that in cancer cell driven by NOTCH1 mutation, high DAD1 expression level indicates high dependence on its function." (PMID 31039782, 2019). "This identified 67 genes of which 50 have been previously reported to be show some association with cancer (including NOTCH1 and PIK3CA) using PUBMED search." (PMID 31427592, 2019). "NOTCH1 had been assumed to be a canonical driver of esophageal squamous carcinoma as it is mutated in around 10% of cancers." (PMID 31138277, 2019).
cancer (continued). "Targeting Notch signaling has been studied in various cancer types, and particularly in hematological malignancies carrying NOTCH1 mutations." (PMID 31676012, 2019). "COSMIC database analyses revealed that mutation of Pro2514 within the Notch1 CPD (FLTPSPES) accounts for as much as 14.63% of the total Notch1 mutations found across all human cancers." (PMID 30086763, 2018). "While the myeloid-B and myeloid-T phenotypes shared some cancer gene mutations in common, the pattern of somatic mutations differed between the two phenotypes, with significant differences in the frequency of NOTCH1 and RUNX1 mutations." (PMID 29991687, 2018). "Several reports associate Notch1 activity with the onset of senescence in cancer, but the temporal regulation is complicated by the sequence of two distinct phases, necessary for the full acquisition of senescence, and differently regulated by Notch activity." (PMID 30154786, 2018). "In patient-derived cancer xenografts with Notch-1 mutation, the detection of high sensitivity of a gamma secretase inhibitor (gamma secretase is responsible for activation of Notch receptors) confirmed the results." (PMID 30111989, 2018). "Molecularly, the observed inclination towards the cancer stem-like properties was associated with the increased expression level of Notch1, WNT1 (both markers of stemness), NF-κB and Vimentin." (PMID 30005681, 2018). "T-ALL is a malignancy characterized by aberrant Notch signaling, sustained by activating mutations in Notch1 as well as overexpression of Notch3, a Notch paralog physiologically subjected to lysosome-dependent degradation in human cancer cells." (PMID 29643474, 2018). "Activated Notch1 has also been shown to play important roles in virus-associated cancers such as Kaposi’s sarcoma (KSHV) and HCV- or EBV-associated lymphoma." (PMID 30231940, 2018). "NFX1-123 has been previously shown to expression of two cellular genes important in HPV-associated cancers, hTERT and Notch1." (PMID 29117186, 2017). "In IHCC, the aberrant expressions of Notch1 and Notch4 were reported to be associated with cancer progression." (PMID 27821106, 2016). "Other frequently mutated EAC driver genes included NOTCH1 (N=8 cancers), ARID1A (N=7), CNTNAP5 (N=3), PIK3CA (N=3) and SMARCA4 (N=3)." (PMID 27045317, 2016). "Notch-1 was linked to diverse cellular processes including cell proliferation, apoptosis, and cancer metastasis and angiogenesis." (PMID 27801803, 2016). "Patients who carried NOTCH1 SMs were at a higher risk of cancer recurrence [odds ratios (OR) = 4.5; 95% confidence interval (CI), 1.4–14.1; P = 0.01] and cancer death (OR = 5.8; 95% CI, 1.5–23.0; P = 0.01) than those who carried wild-types." (PMID 27035284, 2016). "Recent studies have shown that NOTCH1 is a critical regulator of human carcinogenesis and has been implicated in multiple steps of cancer development and progression." (PMID 26491213, 2015). "Notch 1 signaling pathway is associated with regulation of cell fate at several distinct developmental stages and has been implicated in cancer initiation and progression." (PMID 25264898, 2014). "WFA has been reported to inhibit Notch1 and downstream signaling genes (Hes1 and Hey1) that have been implicated in cancer initiation and progression." (PMID 25264898, 2014). "This is consistent with previous studies in cancer cells where a Notch1 mutation that leads to constitutive generation of NICD1 results in persistent NF-κB activation." (PMID 24810405, 2014). "Following validation using xenografted cancers and normal tissues with known patterns of NOTCH1 activation, we applied this test to tumors linked to dysregulated Notch signaling by mutational studies." (PMID 23825651, 2013). "NOTCH1 is included as an often abused, prominent cell-fate transcription factor associated with both cancer stem cells and hESC and is, henceforth, termed a cell-fate determining transcription factor." (PMID 23586024, 2013).